Y_RNA (Y RNA )
Gene: Miscellaneous RNA gene on chromosome 22 (42,762,860 to 42,762,959, reverse strand). Ensembl gene ENSG00000200448.
Homologues: Orthologues: macaque Y_RNA (92% identical). Paralogues in human: Y_RNA (83% identical), RNY1P5 (82% identical), Y_RNA (82% identical), Y_RNA (81% identical), Y_RNA (80% identical), RNY1 (79% identical), Y_RNA (79% identical), RNY1P1 (78% identical), Y_RNA (78% identical), Y_RNA (77% identical), RNY1P11 (76% identical), RNY1P2 (76% identical), and 93 more.